HK2 (hexokinase 2)
Diseases named in the same sentence as HK2 in open-access papers (continued):
Sharing a sentence is not in itself a finding about the gene and the disease.
breast cancer (continued). "Notably, high glucose conditions also enhanced IκBα T291 phosphorylation and PD-L1 expression in HER2-positive SK-BR-3 breast cancer cells, suggesting that HK2-regulated PD-L1 expression is independent of HER2 expression." (PMID 37377974, 2023). "Indeed, several glycolytic enzymes are deregulated in human breast cancer, including PKM2 (pyruvate kinase muscle isozyme 2), PFK (phosphofructokinase), and HK2 (hexokinase 2), and the pharmacological inhibition of HK2 has been investigated as a therapeutic strategy." (PMID 37685021, 2023). "Since Zeb1 regulates expression of the glycolytic rate-determining enzymes HK2, PFKP and PKM2 that modulate cancer cell proliferation and/or apoptosis, the function of Zeb1 in aerobic glycolysis at least partly explains the phenotypes induced by Zeb1 depletion in breast cancer cells." (PMID 35246504, 2022). "Moreover, circRNF20 (hsa_circ_0087784), circulated from RNF20 gene exon-3 to exon-5, has been newly identified in breast cancer samples, and promotes the progress and glycolysis of breast cancer by abrogating the miR-487a-mediatied inhibition of the HIF-1α/HK2 axis." (PMID 35915091, 2022). "miR-155 induces HK2 by transcriptional activation by the signal transducer and activator of transcription 3 (STAT3) as a transcriptional activator or post-transcriptional regulation via repression of miR-143a as a negative regulator of HK2 in human breast cancer cells." (PMID 33922649, 2021). "This means that even though HK2 expression increased in breast cancer cells, it is not regulated by PGC1β, indicating that another factor may contribute to its expression." (PMID 31058090, 2019). "Biochemical analyses demonstrated that phosphorylated HK2 Thr473 promoted its protein stability through the chaperone-mediated autophagy (CMA) pathway, and the levels of PIM2 and pThr473-HK2 proteins were positively correlated with each other in human breast cancer." (PMID 29985480, 2018). "To further validate that the macrophoages/TNFα could activate YAP and HK2 in vivo, we evaluated the relevance of CD68+ (highly expressed in blood monocytes and tissue macrophages) staining with YAP or HK2 staining in human breast cancer samples via immunohistochemical staining." (PMID 28945218, 2017). "However, in the context of breast cancer, it remains unclear whether 2-DG directly induces pyroptosis in breast cancer cells, whether cAMP-PKA signalling acts as a key driver of this process, or whether HK2 serves as a central mediator linking metabolic disturbances to inflammatory cell death." (PMID 41415273, 2025). "Moreover, in specific cellular contexts, such as in breast cancer cells, YAP can enhance glycolytic activity to meet energy demands for cancer cell proliferation via activating the Hedgehog pathway and inducing the expression of glycolysis-promoting factors such as HK2 and PFKFB3." (PMID 37681853, 2023). "However, elevated HK2 expression did not affect the overall survival of breast cancer patients." (PMID 36335239, 2022). "Among three compression-upregulated metabolic genes, the protein expression of HK2 and PFKFB3 genes were detected in breast cancer stromal tissues but not in normal tissue." (PMID 31428701, 2019). "Except of BA-mediated decrease in lactate and PKM2 levels in SK-BR-3 cells, and BA-mediated decrease in HK2 and PKM2 levels in MCF-7 cells, BA did not provoke significant changes in glycolytic pathway in breast cancer cells." (PMID 28213701, 2017). "Using transcriptome sequencing data of the CSC subpopulation in SUM149 human breast cancer cell line from GSE132083, we compared the glycolytic gene expression profiles between the CSC group and non-CSC group, and found that SLC2A1, HK2, ALDOA, ENO1, LDHA and PDK1 were upregulated in the CSC group." (PMID 34052833, 2021). "Similarly, in MCF7 breast cancer cells SLC2A1, HK2, and PFKFB3 but not ENO1 or LDHA were strongly induced by hypoxia." (PMID 23866118, 2013).
breast cancer (continued). "Similarly, primary marrow fat cells and adipocyte cell lines trigger metabolic reprogramming of bone metastatic prostate cancer cells by enhancing the expression of PDK1, enolase 2 (ENO2), LDHA as well as HK2 and GLUT1, already mentioned as Notch downstream effectors in breast cancer cells." (PMID 30873026, 2019).
hepatocellular carcinoma (137 papers, 2007 to 2025). A malignant tumor that arises from hepatocytes. "HK2 expression levels are closely associated with tumor grade and mortality in hepatocellular carcinoma and breast metastasis." (PMID 37109475, 2023). "Removal of glucose from hepatocellular carcinoma (HCC) cells inhibits glycolysis associated with the downregulation of the rate-limiting glycolytic enzyme hexokinase 2 (HK2)." (PMID 37059726, 2023). "The enhanced expression of HK2 in hepatocellular carcinoma in rat models has also been reported to be induced by a loss of DNA methylation on the CpG island on the HK2 promoter." (PMID 37109475, 2023). "Elevated HK2 is associated with poor survival of hepatocellular carcinoma, while inhibition of HK2 expression abrogates the tumorigenesis of tumor cells." (PMID 32042322, 2020). "We found that expression of CDK8 is upregulated during DENV2 infection of Huh7 human hepatocellular carcinoma cells, and that this precedes increased expression of two key genes, hexokinase 2 (HK2) and microtubule-associated protein 1 light chain 3 (LC3)." (PMID 32560467, 2020). "Another recent study demonstrated that HK2 deficiency markedly increased the susceptibility of hepatocellular carcinoma cells to the FDA-approved drug, sorafenib, and also enhanced the inhibitory effects of sorafenib on tumor growth in vivo." (PMID 32083006, 2020). "In hepatocellular carcinoma, overexpression of hexokinase 2 is associated with HK2 CpG island hypermethylation and hypomethylation of surrounding promoter regions." (PMID 30967137, 2019). "HK2 was associated with shorter OS in hepatocellular carcinoma, gastric cancer and colorectal cancer." (PMID 27824926, 2016). "PET imaging studies involving viral-induced woodchuck hepatomas suggest glycolytic activity to vary among liver tumors in association with the levels of HK2 activity." (PMID 23071593, 2012). "RNR1 and hexokinase 2 (HK2) are important risk factors in hepatocellular carcinoma (HCC) patients." (PMID 37038181, 2023). "This indicates that GCK expression is essential for the VLDL assembly/secretion pathway and could explain the loss of this crucial metabolic pathway in hepatoma cells expressing HK2 instead of GCK28." (PMID 33594203, 2021). "HK2 expression in hepatocellular carcinoma (HCC) has been shown to be associated with tumor grade and stage as well as increased mortality of HCC, suggesting the biologic and prognostic significance of HK2 in HCC." (PMID 28445971, 2017). "Hexokinase-2 (HK2) and Beta2-adrenergic receptor (Beta2AR) are overexpressed in hepatocellular carcinoma (HCC) tissues and associated with poor prognosis." (PMID 27255554, 2016). "Que reduces HK2 levels in hepatocellular carcinoma (HCC), suppressing HK2-dependent glycolysis and AKT/mTOR signaling to inhibit progression." (PMID 40832602, 2025). "During glucose shortage, hepatocellular carcinoma cells regulate HK2 levels by elevating SESN2 expression, enhancing SESN2 cytoplasmic localization, and decreasing HK2 mRNA half-life, ultimately suppressing glycolysis." (PMID 40642070, 2025). "Hepatocellular carcinoma cells with high expression of HK2 were treated with chrysin, and cell proliferation and glycolysis were inhibited, while HK2 content in mitochondria was significantly reduced." (PMID 39991762, 2025). "The study suggests that HK2 is typically the sole expressed hexokinase in hepatocellular carcinoma (HCC) cells." (PMID 40028341, 2025). "Hepatocellular carcinoma (HCC) cells exhibit high affinity for HK2 in metabolism and inhibit the expression of glucokinase." (PMID 39991762, 2025). "In hepatocellular carcinoma, hexokinase 2 (HK2), a rate-limiting enzyme in glycolysis, is recognized by the autophagy receptor SQSTM1 and subsequently subjected to selective degradation via the autophagy process." (PMID 38291438, 2024).
hepatocellular carcinoma (continued). "Our findings revealed that the overexpression of HK2 partially counteracted the inhibitory effects of USP14 on various biological functions of hepatocellular carcinoma cells, including proliferation, invasion, migration, glycolysis, and apoptosis promotion." (PMID 38383348, 2024). "MJ is a drug that was found to increase necrosis and apoptosis in hepatocellular carcinoma cells by detaching HK2 from a voltage-dependent anion channel and inhibited glycolysis." (PMID 37529037, 2023). "Another ginsenoside, compound K (CK), attenuated AKT/mTOR/c-Myc signaling in hepatocellular carcinoma, which also led to HK2 and PKM2 suppression and apoptosis." (PMID 38001865, 2023). "Collectively, these results suggest that AG decreases hepatocellular cancer cells proliferation by reducing HK2 expression via augmenting miR-125b expression." (PMID 37920216, 2023). "A recent study revealed that HK2 is aberrantly expressed in hepatocellular cancer cells (HCC) and promotes HCC tumorigenesis." (PMID 38082439, 2023). "MiR-3662 and miR-125a act as suppressors for glucose metabolism by HK2 inhibition, and suppress cell proliferation, invasion, or apoptosis in hepatocellular carcinoma cells in vitro." (PMID 37019900, 2023). "In hepatocellular carcinoma, a significant correlation was observed between HK2 mRNA and HIF-Iα protein levels." (PMID 36984785, 2023). "lornitamine, 3-Bromopyruvate, and 2-deoxyglucose inhibit glycolysis by targeting HK2 in glioblastoma and hepatocellular carcinoma and promoting chemo-sensitivity." (PMID 37524692, 2023). "Studies revealed that inhibiting HK2-mediated glycolysis can enhance the anti-hepatocellular carcinoma activity of sorafenib." (PMID 36335239, 2022). "In hepatocellular carcinoma, HK2 knockout can inhibit glycolysis promoting oxidative phosphorylation of glucose and increase the sensitivity of cancer cell lines to metformin." (PMID 35265223, 2022). "GCK is the first rate-limiting enzyme of glycolysis in normal hepatocytes whose expression is replaced by the hexokinase 2 (HK2) isoenzyme in hepatocellular carcinoma cell lines." (PMID 35055105, 2022). "Another recent study revealed that NR2F1-AS1 was increased under hypoxia and contributed to hypoxia-triggered glycolysis and migration via regulating the miR-140/HK2 pathway in hepatocellular carcinoma (HCC)." (PMID 35283481, 2022). "As an essential rate-limiting enzyme in glycolysis, HK2 has been reported to be actively involved in glycolysis-related liver diseases, especially in hepatocellular carcinoma." (PMID 36431990, 2022). "Another study indicated that the knockdown of HK2 in hepatoma cells suppressed tumor formation via the modulation of glycolysis and oxidative phosphorylation." (PMID 33498721, 2021). "Silencing HK2 in human hepatocellular carcinoma cells inhibits tumorigenesis and increases cell death, and HK2 silencing can synergistically inhibit tumor growth with sorafenib." (PMID 34217310, 2021). "We noted overexpression of another crucial rate-limiting glycolytic enzyme hexokinase 2 (HK2) that has been correlated with poor patient prognosis and aberrant expression patterns in several cancers as hepatocellular carcinoma and others." (PMID 34831316, 2021). "We discovered that CTB inhibited aerobic glycolysis and cell acidification by impairing the activity of HK2 in hepatoma cells, accompanied by dissociation of HK2 from mitochondria." (PMID 31994339, 2020). "QUE reduced the level of HK2 and suppressed Akt/mTOR signalling in hepatocellular cancer lines (SMMG-7721, BEL-7402) in vitro." (PMID 32843908, 2020). "Hexokinase 2 (HK2) is the major isoform that is overexpressed in cancers and its depletion can ameliorate the outcomes in a model of hepatocellular carcinoma." (PMID 32318352, 2020). "DeWaal and colleagues demonstrated that the inhibition of HK2 repressed glycolysis and induced oxidative phosphorylation in hepatomas." (PMID 32331347, 2020).
hepatocellular carcinoma (continued). "Chrysin administration (15, 30, and 60 mM) reduces the expression of HK-2 in hepatocellular carcinoma (HCC) cells to impair glucose uptake and lactate production." (PMID 32992587, 2020). "Promoter hypomethylation of hexokinase 2 (HK2), a Warburg effect mediator, increase HK2 gene transcription and protein availability, favoring glycolytic flux in hepatocellular carcinoma and glioblastoma." (PMID 31366176, 2019). "HK2 is the first rate-limiting enzyme of the glycolytic pathway and silencing HK2 in hepatocellular carcinoma inhibits glucose flux to pyruvate and lactate, leading to cell death." (PMID 30619850, 2018). "Specifically, hexokinase 2 (HK2) upregulation in hepatocellular carcinoma and glioblastoma results from promoter hypomethylation, favoring glycolytic flux." (PMID 30356832, 2018). "Hepatocellular carcinoma (HCC) cells are metabolically distinct from normal hepatocytes by expressing the high-affinity hexokinase (HK2) and suppressing glucokinase (GCK)." (PMID 29386513, 2018). "Goldin in 2008 showed that MJ binds to and detaches mitochondria-bound HK, and, HK2 is highly expressed in hepatoma." (PMID 28498814, 2017). "A recent report showed that HK2 overexpression is associated with the hypomethylation status of CpG island region −379 to +209 from HK2 promoter in hepatocellular carcinomas." (PMID 29285270, 2017). "In agreement, previous studies have indicated that resveratrol downregulates HK2 inducing apoptosis in hepatocellular carcinoma; however the involvement of an epigenetic regulatory event was not described." (PMID 27355345, 2016). "Recently, overexpression of HK2 has been reported in various solid tumors, including colorectal cancer, hepatocellular carcinoma, ovarian cancer, and pancreatic cancer, indicating that HK2 plays an important role in the development and progression of cancer." (PMID 27824926, 2016). "In the present study, we investigated the inhibitory effect of resveratrol on HK2 expression and hepatocellular carcinoma (HCC) cell glycolysis." (PMID 25938543, 2015). "In conditions of low oxygen tension, hypoxia-indicuble factor-1 alpha (HIF-1) has also been shown to upregulate HK2 expression and stimulate the proliferation of hepatoma cells." (PMID 23071593, 2012). "Such intratumoral heterogeneity in immunohistochemical expression was evident in a study of xenograft hepatomas, where HK2 expression was noted to differ between the tumor center and periphery." (PMID 23071593, 2012). "Co-expression of HIF-1 and HK2 has also been found to disproportionately localize in the central portions of hepatomas as well as to areas surrounding tumoral necrosis." (PMID 23071593, 2012). "Considering that HK-2 overexpression is observed in most hepatocellular carcinoma tissues, these results suggest that chrysin or its analogs could be effective drugs in treating hepatocellular carcinoma." (PMID 40872553, 2025). "Similarly, morusin (flavonoid) and tanshinone IIA (diterpenoid) inhibit hepatocellular carcinoma and oral squamous cell carcinoma, respectively, with the suppression of HK2 enzyme." (PMID 39765841, 2024). "The hexokinase isoenzyme (HK2) elevates innate immunity in hepatocellular carcinoma." (PMID 36482897, 2022). "Additionally, in hepatomas, HK2 has been found to be highly expressed in tumor cells, accompanied with great G6P production, and G6P was an important carbon and energy source in hypoxic conditions." (PMID 36289463, 2022). "In hepatocellular carcinoma, limonin promotes a translocation of HK2 from mitochondria to the cytoplasm by inhibiting Akt-mediated phosphorylation of HK2, thereby reducing HK2 activity, further activating BAX, and causing the release of the apoptotic factor cytochrome c." (PMID 36339566, 2022). "However, it has been proved in the literature that ‘Hsa_circ_0001806 promotes glycolysis and cell progression in hepatocellular carcinoma through miR-125b/ hexokinase 2.’." (PMID 35030979, 2022).
hepatocellular carcinoma (continued). "A previous study indicated that STAT3 could promote aerobic glycolysis through targeting hexokinase 2 in hepatocellular carcinoma." (PMID 34195079, 2021). "In other types of cancer, HK2 is often the most abundant HK isoenzyme and may play a more important role, as higher chemosensitivity to metformin following HK2 depletion has been reported in lung and hepatocellular carcinomas." (PMID 34895333, 2021). "HK2 depletion was shown to inhibit glycolysis in hepatocellular carcinoma and increased cell death." (PMID 33101378, 2020). "Hexokinase 2 (HK2) is selectively upregulated in hepatocellular carcinoma (HCC)." (PMID 29386513, 2018). "HK2 expression is controlled by various transcription factors and epigenetic alterations and is heterogeneous in hepatocellular carcinomas (HCCs), though the cause of this heterogeneity is not known." (PMID 27260001, 2016). "3-BrPA might promote the dissociation of -phosphorylated- HK2 from mitochondria in T24, as previously shown in leukemia and hepatocellular carcinoma cells." (PMID 26198749, 2015). "MiR-3662 suppresses glucose metabolism, growth, and invasion of hepatocellular carcinoma cells (HCC) by targeting HK2." (PMID 37019900, 2023). "Mammalian cells possess four HK isoforms (HK1, HK2, HK3, and HK4) although HK2 is the predominant enzyme expressed by cancer cells including hepatocellular carcinoma (HCC)." (PMID 37059726, 2023). "In hepatocellular carcinoma (HCC), NaB inhibits aerobic glycolysis by modulating c-myc signaling-related hexokinase 2 (HK2) expression." (PMID 37100764, 2023). "For instance, it has been reported that CSN5 attenuates HK2 degradation by ubiquitination through its deubiquitinase function to promote hepatocellular carcinoma (HCC) metastasis." (PMID 37190313, 2023). "It is also observed that the GCK to HK2 switch occurs in hepatocellular carcinoma (HCC), and the expression of HK2 is highest in HCC." (PMID 37109475, 2023). "Interestingly, knocking down (KD) of ncRNA-TUG1 and suppressing the miR-455-3p expression leads to decreased activity of adenosine monophosphate–activated protein kinase subunit b2 (AMPKb2), which in turn affects HK2 and reduces the migration and invasion of hepatocellular carcinoma (HCC) cells." (PMID 37384249, 2023). "Therefore, we hypothesized that HK2 may play a key role in the inhibition of glycolysis in hepatoma cells by CTB." (PMID 31994339, 2020). "Also, in agreement with our findings, some studies have shown that decreased HK2 expression resulted in decreased cell proliferation, increased apoptosis, and diminished tumor growth in glioblastoma, colon cancer, thyroid cancer and hepatocellular carcinoma." (PMID 29220380, 2017). "Signal transducer and activator of transcription 3 (STAT3) and hexokinase 2 (HK2) are involved in hepatocellular carcinoma (HCC)." (PMID 28445971, 2017). "In human carcinomas, including hepatocellular carcinoma (HCC), HK2 is highly expressed to produce more energy to support accelerated growth." (PMID 25938543, 2015). "This study examines the protein expression of HK2 and CKA in hepatocellular carcinoma (HCC) in association with patient survival and other clinicopathologic parameters." (PMID 23071593, 2012). "Compound 23 inhibited glycolysis and induced apoptosis in hepatocellular carcinoma (HCC) cells both in vitro and in vivo, through inhibition of HK-2 (which was found to be overexpressed in the majority of HCC tissue) and tumor glycolysis and activation of mitochondria-associated apoptosis." (PMID 40941984, 2025). "For example, pericytes from hepatocellular carcinoma (HCC) and non-small cell lung cancer (NSCLC) take part in vibrant glycolysis triggered by hexokinase 2, detrimentally impacting vessel support function via the ROCK2-MLC2 axis." (PMID 39861125, 2025).